SETDB1 (SET domain bifurcated histone lysine methyltransferase 1)
Diseases named in the same sentence as SETDB1 in open-access papers (continued):
Sharing a sentence is not in itself a finding about the gene and the disease.
oral cancer (1 paper, 2024). "In the nucleus, histone-modifying enzymes, such as SETDB1, SUV39H2, and KMT2A were also associated with areca nuts, suggesting that areca nut-induced mutations also deregulate the expression and silencing of various genes that can promote oral cancer development and progression." (PMID 39027148, 2024).
osteoporosis (1 paper, 2022). A condition of reduced bone mass, with decreased cortical thickness and a decrease in the number and size of the trabeculae of cancellous bone (but normal chemical composition), resulting in increased fracture incidence. "Given that disuse osteoporosis is a systemic bone disease, we further explored the effect of the systemically targeted silencing of Setdb1 in vivo on bone formation." (PMID 36010655, 2022). "In summary, our study reports for the first time that Setdb1 promotes osteoblast proliferation by regulating Macrod2 expression with the assistance of Atf7ip under mechanical unloading, which may aid in establishing a potential therapeutic strategy against osteoporosis." (PMID 36010655, 2022).
ovarian serous cystadenocarcinoma (1 paper, 2022). A malignant serous cystic epithelial neoplasm arising from the ovary. "The results showed that SETDB1 expression was significantly associated with immune subtypes in BLCA, COAD, KICH, KIRC, LIHC, LUAD, LUSC, ovarian serous cystadenocarcinoma (OV), SARC, STAD, and TGCT." (PMID 35656340, 2022).
pancreatic ductal carcinoma (1 paper, 2023).
renal carcinoma (1 paper, 2023). A carcinoma arising from the epithelium of the renal parenchyma or the renal pelvis. "On the other hand, overexpression of VHL induced downregulation of SETDB1 in VHL-deficient renal carcinoma cells." (PMID 37850636, 2023).
sarcoma (1 paper, 2022). A usually aggressive malignant neoplasm of the soft tissue or bone. "SETDB1 expression in GBM, BRCA, ESCA, SARC (Sarcoma), and PRAD was significantly associated with tumor T classification." (PMID 35656340, 2022).
Shock (1 paper, 2016). The state in which profound and widespread reduction of effective tissue perfusion leads first to reversible, and then if prolonged, to irreversible cellular injury. "In this study, we demonstrated that macrophage-specific Setdb1 KO mice show increased susceptibility to the LPS-induced septic shock." (PMID 27349785, 2016).
uterine carcinosarcoma (1 paper, 2022). A usually aggressive malignant neoplasm arising from the uterine corpus and less often the cervix. "Additionally, the clinicopathological grade of LUSC, UCS (uterine carcinosarcoma), and SARC is associated with SETDB1 expression." (PMID 35656340, 2022).
uveal melanoma (1 paper, 2022). A melanoma derived from melanocytes of the uveal tract. "Furthermore, for uveal melanoma (UVM) and TGCT patients, the SETDB1 expression levels in cancers at advanced clinicopathological stages were significantly lower than those in tumors at early stages, implying that decreased SETDB1 expression may indicate the tumor progression in these patients." (PMID 35656340, 2022).
Werner syndrome (1 paper, 2025). "Likewise, lamin A (LMNA) deficiency and the depletion of the DNA repair gene WRN, which occurs in Werner Syndrome (WS) and causes premature aging, leads to H3, SETDB1, SUV39H1 and HP1 deregulation, contributing to heterochromatin loss and DNA damage." (PMID 40886198, 2025).
cancer (110 papers, 2012 to 2026). A tumor composed of atypical neoplastic, often pleomorphic cells that invade other tissues. "Overexpression of SETDB1 is associated with aggressive phenotypes in cancers, such as breast, colon, liver, lung, and myeloid leukemia, where its activity promotes rapid cell growth, proliferation, and immune evasion." (PMID 39764697, 2025). "Amplification of SETDB1 is associated with segmental duplication events in repression domains of cancer cells that are enriched for immune gene clusters (e.g., IFN gene, Fcγ receptor gene, and ULBP1/RAET1 family gene clusters)." (PMID 39133578, 2024). "Evidence in support of this occurring in cancer includes loss of SET Domain Bifurcated Histone Lysine Methyltransferase 1 (SETDB1), an epigenetic regulator of TE expression, resulting in TE upregulation in murine models of lung cancer and melanoma." (PMID 37990347, 2023). "As an important epigenetic enzyme, up-regulation of SETDB1 has been observed in various cancer types, and its overexpression has been linked to poor prognosis." (PMID 37915765, 2023). "In this study, the pan-cancer analysis demonstrated that SETDB1 showed significantly differential expression in most tumor tissues and paracancerous tissues, and SETDB1 expression was associated with clinicopathological features and clinical prognosis." (PMID 35656340, 2022). "In human cancers, the expression of SETDB1 is inversely correlated with several hallmark gene signatures related to immune response." (PMID 35455671, 2022). "According to our results, the association between SETDB1 expression and HLA-related genes varies markedly among cancer types." (PMID 35656340, 2022). "Given that SETDB1 genetic alterations were associated with molecular therapeutic targets for various human cancers, we investigated the genetic alteration levels of SETDB1 in various human cancers based on TCGA datasets." (PMID 35656340, 2022). "Recently, SETDB1-dependent ERV repression in cancer cells was also confirmed to be associated with evading recognition by the immune system." (PMID 34299035, 2021). "In vitro and in vivo experiments showed that SETDB1 overexpression was associated with elevated cell growth rates and invasive potential of cancer cells in nude mouse models." (PMID 31398867, 2019). "SETDB1 is implicated in the formation of the cancer stem cells that give rise to metastases through a variety of mechanisms such as metabolic pathways and EMT." (PMID 31405032, 2019). "This study focused on the early time point of acquired drug resistance in cancer, therefore SETDB1/2 mediated increment of H3K9me3 mark along with concomitant loss of H3K4me3 is limited to the early phase of stress tolerance in cancer." (PMID 29492189, 2018). "Following the observation that SETDB1-high tumors are enriched in poorly differentiated and stem-like subclasses, we investigated whether SETDB1 expression is functionally associated with cancer stemness programs in HCC." (PMID 41493679, 2026). "SETDB1 gain-of-function mutations promote proliferation, invasion and migration of cancer cells." (PMID 39945463, 2025). "Also, great progress has been made in elucidating the underlying mechanisms of SETDB1 regulation and its functional implication in different cancers." (PMID 39583200, 2024). "SETDB1 accumulation may underlie a molecular mechanism for VHL inactivation involved in cancer progression." (PMID 37850636, 2023). "Finally, transcriptome analysis of human cancer disclosed that SETDB1 expression is inversely associated with dsRNA responses along with innate immune-inflammatory pathways in hypoxic cancer." (PMID 37850636, 2023).
cancer (continued). "To investigate whether SETDB1 is associated with hypoxic response in clinical samples, we analyzed transcriptomic features associated with its expression in patients with hypoxic cancer." (PMID 37850636, 2023). "Elucidation of the regulatory mechanism of SETDB1 translocation is important for superintending its activity, as it is causally related to a variety of cancers as an oncogene and is thus considered a promising therapeutic target for cancer immunotherapies." (PMID 36605719, 2022). "SETDB1 is overexpressed in various cancer types and is associated with an aggressive phenotype." (PMID 36330589, 2022). "Aberrant SETDB1 expression is observed in various cancers and is associated with carcinogenesis." (PMID 36048239, 2022). "The overexpression of SETDB1 has been reported to induce the modulation of genes associated with various signaling pathways, including those for tumorigenesis and those that promote cancer invasion and progression." (PMID 31768101, 2019). "Importantly, SETDB1 protein overexpression was associated with elevated cell growth rates and the invasive potential of cancer cells in nude mouse models." (PMID 31398867, 2019). "Furthermore, SETDB1 has been shown to be associated with drug resistance in cancers." (PMID 38317200, 2024). "Our demonstration that SETDB1 loss in hypoxia robustly de-represses TEs, triggering DNA damage-induced cell death, suggests that targeting SETDB1 could serve as a useful therapeutic strategy for directed treatment of cancer cells in the hypoxic TME." (PMID 37850636, 2023). "Therefore, aberrant trimethylation at H3K9 due to amplification, mutation or deletion of SETDB1 may lead to transcriptional repression of various tumour-suppressing genes and other related genes in cancer cells." (PMID 34299035, 2021). "Furthermore, to evaluate whether the association of SETDB1 mRNA levels with smoking status correlated with a cancer subtype, subgroup analyses were performed for ADC patients." (PMID 31398867, 2019). "Interestingly, mutations in or loss of SETDB1 have been reported in cancer." (PMID 30103804, 2018). "A more frequent expression of SETDB1 was found in malignant cells from both cancer types, with a slightly higher tendency in iCCA-derived cells compared to HCC ones." (PMID 41493679, 2026). "While essential for normal immune cell function, SETDB1 overexpression in cancer cells disrupts immune responses by suppressing tumor immunogenicity and facilitating immune evasion." (PMID 39764697, 2025). "SETDB1, commonly overexpressed in various cancers, plays a critical role in immune regulation and tumor progression." (PMID 39764697, 2025). "Collectively, our results demonstrate that SETDB1 KO or inhibition results in cell type-specific derepression of TEs in cancer cell lines." (PMID 40610675, 2025). "SETDB1, a lysine methyltransferase, is pivotal in silencing tumor suppressor genes and plays a significant role in various cancer pathways." (PMID 39764697, 2025). "Epigenetic deregulation of SETDB1 expression appears to be involved in different cancers types, particularly in aggressive, relapsing or treatment-resistant subtypes." (PMID 39945463, 2025). "Future research should focus on understanding SETDB1's mechanisms across different cancer types, developing SETDB1‐specific inhibitors, and mapping its role in immune regulation to refine therapeutic strategies." (PMID 39764697, 2025). "Setdb1 overexpression in cancers enhances immune evasion by restricting antigen presentation of retrotransposon-derived peptides." (PMID 40339988, 2025).
cancer (continued). "Despite these challenges, SETDB1 remains an exciting therapeutic target, particularly in overcoming immune resistance mechanisms in cancer." (PMID 39764697, 2025). "SETDB1's dysregulation also affects immune cell development and function, with its inhibition enhancing immune responses and potentially improving cancer outcomes." (PMID 39764697, 2025). "Given that AKT1 hyperactivation is associated with poor prognosis in several cancers, this role of SETDB1 further underscores its importance in cancer progression." (PMID 39945463, 2025). "This review explores SETDB1's dual function in immune regulation and tumor progression, emphasizing its potential in the development of innovative cancer treatments targeting epigenetic dysregulation and oncogenic signaling." (PMID 39764697, 2025). "Given the important role of SETDB1 in tumorigenesis, progression, metastasis, and tumor immune escape, the development of SETDB1 inhibitors is a promising strategy for cancer chemotherapy and immunotherapy." (PMID 39583200, 2024). "Repression of Alu, mediated by SETDB1, an enzyme that deposits the H3K9me3 mark on Alu sequences, was observed in cancer cells." (PMID 39775734, 2024). "Researches have shown that SETDB1 is upregulated in majority of cancers and promotes cancer malignant biological behavior." (PMID 38317200, 2024). "So far, the abnormal expression and poor prognosis of SETDB1 in various cancers have demonstrated its role as an oncogene." (PMID 39583200, 2024). "SETDB1 has recently gained recognition as a protein that aids cancer cells in evading the immune system and holds potential as an novel target for cancer treatment." (PMID 39026989, 2024). "It has been reported that the histone methyltransferase SETDB1 is overexpressed in most cancer types, and its induced aberrant methylation of H3K9 is an important player in epigenetics and is involved in the genesis of a variety of cancers." (PMID 39583200, 2024). "Recent advances with CRISPR screening improve the feasibility of identifying vital epigenetic regulators (e.g., MLL4 and SETDB1) that mediate the interplay between cancer cells and T cells." (PMID 39133578, 2024). "In cancer cells, upregulation of SETDB1 inhibits the production and infiltration of antitumour immune cells, interferes the expression of PD-L1, disrupts type I interferon response, and IFN signaling." (PMID 38317200, 2024). "To investigate the possible role of SETDB1 in tumor pathogenesis, we analyzed the gene expression of SETDB1 in several human cancers from TCGA." (PMID 39768193, 2024). "The study also pinpointed that the expression of SETDB1 correlates with immune and molecular cancer subtypes, as well as immune checkpoint- and HLA-related genes (human leukocyte antigen-related genes)." (PMID 39519018, 2024). "Some studies have shown that disruption of the ATF7IP-SETDB1 complex in tumor cells can restore the expression of tumor antigens, which provides a rationale for cancer immunotherapy targeting SETDB1 or ATF7IP." (PMID 39583200, 2024). "In squamous cell carcinoma, enhancer of zeste homolog 2 (EZH2) inhibits RUNX3 (RUNX Family Transcription Factor 3) expression to activate both SETDB1 and ΔNp63α, which drives an aggressive cancer stem cell phenotype." (PMID 38057834, 2023). "An elevated expression of SETDB1 in numerous types of cancers, leading to increased repression of repeat elements has previously been reported." (PMID 37697430, 2023). "SETDB1‐mediated MCT1 tri‐methylation at K473 enhances cancer cell glycolysis and promotes M2‐like macrophage polarization of TAMs." (PMID 37541664, 2023). "Cancer cells overexpress SETDB1 to regulate the methylation of histones to facilitate cancer evasion from immune surveillance." (PMID 39872303, 2023).
cancer (continued). "In cancer, overexpression of SETDB1 negatively correlates with a characteristic gene signature associated with a positive immune response." (PMID 37394580, 2023). "Our results clearly imply that the suppressive effects of SETDB1 on endogenous dsRNA production from TEs and subsequent inflammatory responses are more significant in hypoxic than normoxic cancer cells." (PMID 37850636, 2023). "SETDB1 targeting is a promising approach to cancer therapy, particularly immunotherapy, because of its regulatory effects on endogenous retroviruses." (PMID 36582533, 2022). "In this study, the dysregulated proliferation and cell cycle process in SETDB1-KD SSCs were similar to the phenotypes in cancer cells." (PMID 35159180, 2022). "SETDB1 is aberrantly expressed in a wide variety of human cancers, facilitating tumor development and drug resistance." (PMID 35372573, 2022). "Growing evidence has revealed the close correlation of SETDB1 overexpression and abnormal activity in a variety of malignancies with an unfavourable prognosis of cancer patients." (PMID 36582533, 2022). "Given the important role of SETDB1 in cancer treatment, our study suggests possible potential research and therapeutic directions." (PMID 36077559, 2022). "Although challenged by its functions in normal cells and potential side effects, increasing evidence nevertheless strongly supports SETDB1 as a candidate target for cancer therapy, particularly immunotherapy." (PMID 36582533, 2022). "SETDB1 is a histone methyltransferase that has been reported to be involved in progression of diverse cancer types." (PMID 35184652, 2022). "It is expected that the investigation and characterization of SETDB1 biological function can help to identify the key targets and regulatory pathways and promote human cancer treatment in the future." (PMID 35656340, 2022). "Further, SETDB1 mediated Akt K64 methylation promotes Akt hyperactivation resulting in cancer progression." (PMID 35395812, 2022). "As SETDB1 overexpression and its oncogenic role is evident in a broad range of cancers, SETDB1 is spotlighted as a promising target for therapeutic interventions." (PMID 36605719, 2022). "In order to evaluate the prognostic abilities of SETDB1 in these cancers, independent clinical factors were selected as the subgroups." (PMID 35656340, 2022). "The H3K9 methyltransferase SETDB1 is over-expressed or amplified in various cancer types, correlating with poor patient survival." (PMID 35602594, 2022). "We also demonstrated a significant correlation between SETDB1 expression and each immune checkpoint-related gene (immunoinhibitor and immunostimulator) in diverse cancers in TCGA." (PMID 35656340, 2022). "Given the important role of SETDB1 in tumourigenesis, progression, and tumour immune escape, developing SETDB1 antagonists is a promising strategy for cancer chemotherapy and immunotherapy." (PMID 36582533, 2022). "For example, SETDB1 stabilizes Th2 cells by blocking ERVs that shape the Th1 gene network while promotes cancer metastasis by multiple mechanisms." (PMID 34294683, 2021). "SETDB1 is activated or inhibited in various cancers and plays a key role as oncoprotein or tumour suppressor." (PMID 34299035, 2021). "More importantly, the expression of SETDB1 is upregulated in a variety of tumours, indicating that SETDB1 is closely related to the occurrence and development of cancers." (PMID 34299035, 2021). "Overexpression and downregulation of SETDB1 have been widely found in various cancers, but the detailed mechanisms are still unclear." (PMID 34299035, 2021). "Altogether, SETDB1 activity results in higher aggressiveness and worse cancer prognosis and has therefore been regarded as an oncogene." (PMID 34440561, 2021). "SETDB1 knockdown was shown to promote G0/G1 phase arrest, decrease colony formation and suppress cancer growth and migration." (PMID 34440561, 2021).